ENSG00000199321
Synonyms: LOC124900294
Gene: Small nucleolar RNA gene on chromosome 10 (126,779,702 to 126,779,774, reverse strand). Ensembl gene ENSG00000199321.
Gene Ontology:
Biological process: RNA processing
Cellular component: nucleolus
Homologues: Paralogues in human: SNORD60 (86% identical).